GSTM1 (glutathione S-transferase mu 1)
Diseases named in the same sentence as GSTM1 in open-access papers (continued):
Sharing a sentence is not in itself a finding about the gene and the disease.
cancer (continued). "The role of GSTM1 in chemotherapy efficacy and cancer prognosis draws much attention." (PMID 30032483, 2018). "GSTM1 and GSTT1 homozygous deletions are associated with reduced detoxification function, increased susceptibility to cytogenetic damage, and increased risk of cancer." (PMID 27911277, 2017). "Our results are in accordance with previous reports that null genotypes of GSTT1 and GSTM1 could be a poorer prognosis and showed a sluggish response to chemotherapy in various types of cancers." (PMID 29285301, 2017). "In accordance with their detoxification properties, the deficiencyof GSTM1 and GSTT1, either individually or incombination, greatly increases the susceptibility of developing cancer in differentorgans, including liver, lung and colon (Csejteiet al., 2008; Suiet al., 2014; Zhanget al., 2014b)." (PMID 29111561, 2017). "Furthermore, Gstm1, a member of the glutathione S-transferase family that inhibit p38 activation by oxidative stress, is overexpressed in multiple types of cancers." (PMID 28460458, 2017). "Therefore, the existence of the GSTM1 gene and mRNA was checked here in 8 bladder cell lines including 7 cancer types and one SV40-transformed normal cell type." (PMID 27404495, 2016). "Trends in variability of GSTM1 and GSTT1 null genotypes within a given population might help to estimate the risk of subjects in the development of certain cancers." (PMID 25969820, 2015). "As important phase II enzymes, the GSTM1 and GSTT1 null genotypes are known to eliminate enzyme activities; therefore, these null genotypes have been linked with the increased number of cancer cases, possibly due to increased susceptibilities to environmental toxins and carcinogens." (PMID 25789067, 2015). "Specifically, a significant inverse association between intake of carotenoid-rich or cruciferous vegetables and cancer risk was detected in carriers of the GSTM1- or GSTT1-present genotype but not in those participants with the GSTM1- or GSTT1-null genotype." (PMID 26580648, 2015). "Because GSTM1 and GSTT1 are involved in the detoxification of a variety of compounds, and their substrates often overlap, it is possible that individuals with a more defective genotype of these genes can be expected to at higher risk of cancers." (PMID 25477765, 2014). "Previous studies showed that a homozygous deletion or null genotype, at either the GSTM1 locus or the GSTT1 locus resulted in enzyme function loss, and thus it was hypothesized to be related to the susceptibility to cancer." (PMID 24250808, 2013). "The meta-analysis and pooled analysis indicated that both GSTM1 null genotype (null vs. present: OR = 2.66; 95%CI = 2.19–3.14) and GSTT1 null genotype (null vs. present: OR = 2.46; 95%CI = 1.83–3.32) were associated with an increased cancer risk in smokers." (PMID 24250808, 2013). "Stratification analyses of the GSTM1 and GSTT1 polymorphism on cancer." (PMID 24250808, 2013). "The GSTM1, GSTT1 and GSTP1 polymorphisms might be involved in inactivation of procarcinogens that contribute to the genesis and progression of cancers." (PMID 23189206, 2012). "Taken together, these results indicate that GSTM1 and GSTT1 homozygous deletion polymorphisms may yield different effects on different types of cancers." (PMID 21629772, 2011). "Previous evidence suggests that GSTM1 and GSTT1 polymorphisms may have a close association with increased susceptibility to various carcinomas." (PMID 19338664, 2009). "Similar to GSTM1, GSTT1 has significant activity towards epoxides, suggesting that individuals without both GSTM1 and GSTT1 may be at a particularly high risk of cancer." (PMID 12556960, 2003). "The glutathione S-transferase genes GSTM1 and GSTT1 are another pair of copy-number variable genes in HG002 that play a role in the neutralization of toxic compounds, with homozygous deletions (null alleles) being linked to an increased risk of cancer in certain populations." (PMID 41000953, 2025).
cancer (continued). "In addition to GSTP1, the activity of GSTM1 and GSTT1 may be partly implicated in the response to platinum-based cancer treatment and the detoxification of platinum compounds." (PMID 39903276, 2025). "But the interaction of GSTM1-null and drinking might increase cancer risks in Caucasian drinkers." (PMID 38579033, 2024). "The combined GSTM1 null and GSTT1 null led to a significant risk; similarly, the combined GSTM1 null and GSTP1 Ile/Val or Val/Val genotypes as well as the GSTT1 null and GSTP1 Ile/Val or Val/Val genotypes significantly increased the individuals’ susceptibility to cancer." (PMID 39595582, 2024). "Deletion polymorphism of the GSTM1 gene leads to the complete absence of protein, meaning a complete lack of enzyme activity, which could further result in increased susceptibility to carcinoma development in carriers of the GSTM1-null genotype." (PMID 38674199, 2024). "Thus far, two cancer patients from the cohort exposed to pesticides have already died; one of them was a heterozygous carrier of the GSTM1 gene deletion, and the other was homozygous for the GSTM1 deletion (sample codes UZH 15 and UZH 37)." (PMID 38133349, 2023). "However other studies failed to establish the association between GSTM1 null and the risk of several types of cancers." (PMID 31646988, 2019). "The common variants of GSTM1 and GSTT1 genes is the homozygous deletion (null genotype), which has been reported to causes the loss of enzymic activity and might higher the risk of various cancers." (PMID 25477765, 2014). "The availability in the ESCH database of a group of subjects genotyped for GSTM1 and GSTT1 genes in three national laboratories allowed us to address the question if these genetic polymorphisms can modify the strength of the association between CA and cancer risk." (PMID 19270789, 2009). "Thus, the absence of the GSTM1 gene should increase cancer risk from environmental exposure while the presence of the intact GSTM1 gene would be protective for cytogenetic damage and carcinogen-derived DNA adduct formation." (PMID 12556960, 2003). "Considering this role, we aimed to investigate GSTT1, GSTM1 and GSTP1 characterised polymorphic markers in a mixed cohort of cancer patients receiving chemotherapy." (PMID 36939926, 2023). "Given the involvement of GSTs in deactivating and detoxifying carcinogens, deletions in GSTM1 and GSTT1 and IIe105Val polymorphism in GSTP1 resulting in no enzyme activity may compromise an individual’s ability to deactivate carcinogens, thus increasing risk of cancer." (PMID 32155154, 2020). "Among all the GSTs, the GSTM1 and GSTT1 have been extensively found related to various types of cancers." (PMID 30976200, 2019). "GSTM1 and GSTT1 are two subtypes of the Glutathione-S-transferase family of enzymes that can protect against developing cancer." (PMID 28508326, 2018). "The frequencies of homozygous deletion genotypes of GSTM1 and GSTT1 are about 50% and 14% in Caucasians, and the homozygous deletion genotypes of both GSTM1 and GSTT1 were reported to be associated with risk for a variety of cancers and may be linked to alterations in drug metabolism." (PMID 30257855, 2018). "Seven cofactors (TFAP2A, E2F, GSTM1, IL6, PATZ1, MEF2A and GTF2I) identified in two of the five cancer types have general functions in cancers." (PMID 28684851, 2017). "The data showed that only one cancer cell type, T24, possessed the GSTM1 gene and mRNA, while 6 other cancer cell lines and SV-HUC1 belonged to the GSTM1-null genotype." (PMID 27404495, 2016). "GSTM1 belongs to GSTs family which plays a regulatory role in MAP kinase pathway (cellular survival and death signaling) and are involved in various cancers." (PMID 26414287, 2015). "GREAT also reported that HepG2-enriched windows were close to many cancer genes HPX, HPN, LCAT, TST, GSTM1, CEPBA, CYP2B6." (PMID 25522020, 2014).
cancer (continued). "Were this to be the case, these compounds would be more rapidly eliminated through conjugation in GSTM1- and/or GSTT1-carriers, reducing the bioavailability of the putative anti-cancer compound." (PMID 25198353, 2014). "We previously examined GSTM1 and GSTT1 genotypes in 104 cell lines originating from a variety of human malignant tumors and found that GSTT1 null genotype was more common in cervical cancer cells." (PMID 21660264, 2011). "When null, the mu and theta genes of the glutathione S-transferase system (GSTM1 and GSTT1, respectively) are related to malignant tumors affecting the lungs, colon, prostate, bladder and head and neck." (PMID 18094897, 2007). "In all of these studies the GST null genotype (GSTM1 and or GSTT1) has been seen with increased frequency in patients with second cancers in the UADT as compared to those with single cancers in the UADT." (PMID 15790417, 2005). "The GSTM1-null genotype promotes cancers, metabolic and autoimmune disorders, but absence of GSTM1 activity can itself be partially compensated by the overexpression of other GST family members." (PMID 41510264, 2025). "GSTM1-null and GSTT1-null might be related cancers in combination with smoking or drinking, and GSTP1rs1695 might be associated with cancers among drinkers." (PMID 38579033, 2024). "GSTM1 can also activate STAT3 signaling, a key modulator of multiple cellular processes including proliferation, apoptosis, and metastasis, which is altered in multiple types of cancers." (PMID 39726707, 2024). "Investigation into CIPN association with polymorphisms in GSTM1, GSTT1 and GSTP1, identified no significant results in a mixed cancer cohort." (PMID 36939926, 2023). "Both GSTM1 and GSTM2 play important roles in cell detoxification, protecting cells against cancer." (PMID 35008958, 2022). "The significance of the GSTM1 del genotype in Pakistani, Turkish and Belarussian populations with respect to lung malignancy was not confirmed in previous studies." (PMID 35207542, 2022). "The cancer genes are composed of genes that code for HER2 (HER2 and GRB7), oestrogen genes (ER, PGR, BCL2, and SCUBE2), proliferation genes (MKI67, STK15, BIRC5, CCNB1, and MYBL2), and invasion genes (MMP11 and CTSL2) as well as GSTM1, CD68, and BAG1." (PMID 36042999, 2022). "This correlation between CYP1A1, GSTM1, GSTP1, and GSTT1 seems to be important, once this balance between activation and detoxification of carcinogens can influence the development, progression, and prevention of cancer." (PMID 35409669, 2022). "Unlike previous studies contrasting DTC risk in null vs. non-null genotypes, CNVs of GSTM1 and GSTT1 were also examined in our study to investigate a potential dose-effect relationship between enzymatic activity and cancer risk." (PMID 31999731, 2020). "Similarly, GSTA1 contributes to chlorambucil chemoresistance, while through synergism of GSTM1 and MRP-1 cancer cells are protected from vincristine." (PMID 30487385, 2018). "Because WA predominantly increased DNA methylation, we mainly focused on verification of hypermethylation effects obtained for selected genes related to cancer invasiveness (ADAM8, PLAU, and TNFSF12), detoxification (GSTM1) or mitochondrial functions (ME3), in relation to gene expression silencing." (PMID 28467815, 2017). "In the subgroup analysis by ethnicity suggested that a possible association between the null genotype of GSTM1 and GSTT1 with higher risk of cancer in Asians and Caucasians but not in Africans." (PMID 24250808, 2013). "Previous data have suggested that the null genotypes of both GSTM1 and GSTT1 are associated with a slightly increased risk of some forms of cancer, although this does not appear to concern all cancers." (PMID 19270789, 2009). "Individualswith a null GSTM1 and high drinkers would not convert ethanol in acetaldehydeand then the absence of the gene would confer them a protective effect fororopharyngeal cancer." (PMID 19259333, 2008).
cancer (continued). "However, they may also share changes in some genes (like GSTM1 and NAT2) that make it hard for their bodies to break down certain toxins, which can make them more likely to get cancer." (PMID 41018918, 2025). "And subgroup results demonstrated that GSTM1-null might increase cancer risks regardless of ethnicities (Caucasian and Asian) or whether smoking." (PMID 38579033, 2024). "To answer this question, we performed an analyses stratified for smoking in order to assess whether the GSTM1 or GSTT1 null genotype influence on cancer differently for smokers from non-smokers." (PMID 24250808, 2013). "Functional polymorphisms of members of the Glutathione S-transferase family (GSTM1, GSTT1, and GSTP1) are the result of large deletions present in the structural gene, which in turn affect drug metabolism and influence the effects of chemotherapy in cancer patients." (PMID 23319948, 2012). "It was reported that the metabolic action of GST enzymes may differ by cancer site; the highest concentrations of GSTP1 have been observed in oral and pharyngeal tissues, and the highest concentrations of GSTM1 have been observed in laryngeal tissue, relative to the other GSTs." (PMID 23144854, 2012). "We identified females with a paired cancer in the UADT in association with another cancer (at all sites-genital and non-genital) and analyzed GSTM1 and T1 genotype in addition to known factors such as age, tobacco habits, alcohol habits and family history of cancer." (PMID 15790417, 2005). "The comparative analysis of GSTM1 allelotypes in our two populations did not demonstrate a statistically significant difference in distribution (P = 0.22), although the null genotype was more frequent in cancer patients." (PMID 9888479, 1999). "Moreover, numerous studies have shown the link between the lack of enzyme activity in GSTM1 and GSTT1 and the susceptibility to develop various types of cancer, such as oral cancer, gastric cancer, bladder cancer, and CML in different ethnical groups worldwide." (PMID 25969820, 2015). "The negative result concerning the influence of GSTM1 and GSTT1 polymorphisms, despite the intrinsic limitation due to small numbers, is in agreement with the idea that individual polymorphisms are not expected to have a dramatic influence on baseline CA level or overall cancer risk." (PMID 19270789, 2009). "We did not observe differences in GSTM1, GSTP1, or GSTT1 gene expression in the cancer group, but as Phase II enzymes are responsible for detoxification of carcinogens, once cancer is present, it possibly means that the role of these enzymes is not proceeded to neutralize the toxic substances." (PMID 35409669, 2022).
tumor (52 papers, 1995 to 2025). "The role of GSTM1 in tumor cell phenotypes has been shown: knockdown of GSTM1 decreased tumor cell viability and caused cell cycle arrest at G0/G1 phase." (PMID 34732244, 2021). "Further analysis of the cell cycle profile showed that knockdown of GSTM1 caused more tumor cells to be arrested at G0/G1 phase." (PMID 34732244, 2021). "Regarding clinical data, tumor stage provided the highest contribution risk score, and high expression of GSTM1 and GSTM2 showed higher contribution risk scores for COAD patients." (PMID 32539715, 2020). "A meta-analysis of 36 case-control studies also detected a relationship between GSTM1 polymorphism and tumor site." (PMID 29765533, 2018). "Here, we studied the interaction of various habits related factors and polymorphism of GSTM1/GSTT1 genes towards inducing promoter hypermethylation of multiple tumour suppressor genes." (PMID 23596512, 2013). "However, GSTM1‐GSTT‐1 polymorphisms depended on the mtDNA copy number in assessing the tumor stages of OSCC as well as risk of OSCC." (PMID 40256126, 2025). "In addition, some genes (glutathione S-transferase mu 1, cyclin D1and cytochrome P450 family 2 subfamily S member 1) in risk model was show significant difference between normal and tumor tissues." (PMID 36203457, 2022). "Although our study focuses on GSTM5, it is part of the larger GST family, which includes GSTM1 and GSTM2, both of which have been implicated in tumor progression and treatment response." (PMID 40868127, 2025). "Accumulating studies have established a strong correlation between GSTM1 and oxidative stress in various contexts, such as tumor development, neurodegeneration, and so forth." (PMID 40448227, 2025). "In an orthotopic mouse model of HNSCC, mice implanted with GSTM1 knockdown JHU029 cells exhibited a substantial reduction in tumor volume and weight compared to the knockdown control group." (PMID 39044272, 2024). "Effect of GSTM1 knockdown were assessed by cell proliferation, colony formation, and tumor development in an orthotopic mouse model." (PMID 39044272, 2024). "The expression pattern of GSTM1 was validated by immunohistochemistry using tumor tissue microarray (TMA)." (PMID 39044272, 2024). "Strikingly, simultaneous evaluation of the association between GSTM1 expression and the five major clinical characteristics (race, sex, HPV infection status, age and tumor stage) in the TCGA HNSCC cohort." (PMID 39044272, 2024). "Nonetheless, we found 46 genes that carried either genomic or transcriptional alterations in all three resistant tumor groups, including 8 genes (Parp3, Gstm1, Il18, Padi4, Dnmt3b, Psrc1, Rif1, and Ankrd26) involved in DDR." (PMID 37209095, 2023). "The ATAC-sequencing tracks from the genome datasets (short-survival, long-survival, normal tissue) showed high chromatin-accessible regions in the promoter of GSTM1 in certain short-survival tumor samples, consistent with the genomic dataset analysis." (PMID 34732244, 2021). "Heatmap analysis of gene expression and chromatin accessibility showed that GSTM1 had the highest chromatin accessibility in tumor samples with short survival times." (PMID 34732244, 2021). "A previous study showed that GSTM1 induces tumor resistance by hydrolyzing tumor chemotherapy drugs or activating anti-apoptotic pathways, and it was shown to be a negative regulator of apoptosis-related signaling cascades." (PMID 32539715, 2020). "The formula of the F2P Score was developed and presented herein: F2P Score = 0.888 × (1.424 × tumor size-0.667 × age)+0.314 × (−0.259 × ESR1−0.191 × PGR−0.292 × BCL2−0.226 × GSTM1 −0.457 × CD68–0.320 × BAG1)." (PMID 33042787, 2020). "We found that the protein and the mRNA level of Nqo1 and Gstm1 (NRF2 target genes) were drastically elevated in the tumor tissues of the Atg7ΔHep mice." (PMID 32382012, 2020).